HMCES (5-hydroxymethylcytosine binding, ES cell specific)
Description:
Sensor of abasic sites in single-stranded DNA (ssDNA) required to preserve genome integrity by promoting error-free repair of abasic sites. Acts as an enzyme that recognizes and binds abasic sites in ssDNA at replication forks and chemically modifies the lesion by forming a covalent cross-link with DNA: forms a stable thiazolidine linkage between a ring-opened abasic site and the alpha-amino and sulfhydryl substituents of its N-terminal catalytic cysteine residue. Promotes error-free repair by protecting abasic sites from translesion synthesis (TLS) polymerases and endonucleases that are error-prone and would generate mutations and double-strand breaks. The HMCES DNA-protein cross-link is then either reversed or degraded. HMCES is able to catalyze the reversal of its thiazolidine cross-link and cycle between a cross-link and a non-cross-linked state depending on DNA context: mediates self-reversal of the thiazolidine cross-link in double stranded DNA, allowing APEX1 to initiate downstream repair of abasic sites. The HMCES DNA-protein cross-link can also be degraded by the SPRTN metalloprotease following unfolding by the BRIP1/FANCJ helicase. Has preference for ssDNA, but can also accommodate double-stranded DNA with 3' or 5' overhang (dsDNA), and dsDNA-ssDNA 3' junction. Plays a protective role during somatic hypermutation of immunoglobulin genes in B-cells: acts via its ability to form covalent cross-links with abasic sites, thereby limiting the accumulation of deletions in somatic hypermutation target regions. Also involved in class switch recombination (CSR) in B-cells independently of the formation of a DNA-protein cross-link: acts by binding and protecting ssDNA overhangs to promote DNA double-strand break repair through the microhomology-mediated alternative-end-joining (Alt-EJ) pathway (By similarity). Acts as a protease: mediates autocatalytic processing of its N-terminal methionine in order to expose the catalytic cysteine (By similarity).
Synonyms: C3orf37; DC12; SRAPD1
Tractability: PROTAC: UniProt records ubiquitination sites on it; ubiquitination databases record sites on it; its protein half-life has been measured.
Target class: Enzyme; Hydrolase
Gene: Protein-coding gene on chromosome 3 (129,278,441 to 129,306,189, forward strand). Ensembl gene ENSG00000183624.
Subcellular location: Chromosome
Subcellular location (Human Protein Atlas): Nucleoplasm
Gene Ontology:
Molecular function: DNA-(abasic site) binding; DNA-(apurinic or apyrimidinic site) endonuclease activity; protein binding; protein-DNA covalent cross-linking activity; single-stranded DNA binding
Biological process: DNA damage response; interstrand cross-link repair; protein-DNA covalent cross-linking repair; somatic hypermutation of immunoglobulin genes; double-strand break repair via alternative nonhomologous end joining; positive regulation of isotype switching; DNA repair
Cellular component: chromosome; replication fork
Genetic constraint (gnomAD): Loss-of-function variants: 27 observed, 39.9 expected, observed/expected ratio (o/e) 0.68, 90% interval 0.5 to 0.93. The upper end of that interval is the gene's LOEUF score, 0.93, which puts it in group 3 of 6, group 1 being the genes least tolerant of losing a copy. Missense variants: 389 observed, 440.59 expected, observed/expected ratio (o/e) 0.88, 90% interval 0.81 to 0.96. Synonymous variants: 129 observed, 156.27 expected, observed/expected ratio (o/e) 0.83, 90% interval 0.71 to 0.95.
Homologues: Orthologues: chimpanzee HMCES (99% identical), macaque HMCES (99% identical), dog HMCES (88% identical), pig HMCES (84% identical), mouse Hmces (84% identical), rabbit HMCES (84% identical), rat Hmces (84% identical), tropical clawed frog hmces (60% identical), zebrafish hmces (51% identical), Drosophila melanogaster CG11986 (35% identical).
Diseases named in the same sentence as HMCES in open-access papers:
HMCES is named in the same sentence as 12 diseases in open-access papers, as found by Europe PMC text mining. Sharing a sentence is not in itself a finding about the gene and the disease. The quoted sentences say what the papers report.
lung carcinoma (1 paper, 2021). "To test these possibilities, we depleted HMCES in multiple lung cancer cell line backgrounds by shRNA depletion or CRISPR/Cas-9 knockout." (PMID 33788831, 2021).
non-small cell lung carcinoma (1 paper, 2021). A group of at least three distinct histological types of lung cancer, including non-small cell squamous cell carcinoma, adenocarcinoma, and large cell carcinoma. "A genome-scale CRISPR/Cas9 screen identifies HMCES, a suicide enzyme that binds abasic sites, as a major suppressor of A3A-mediated damage in non-small cell lung cancer." (PMID 33788831, 2021).
viral infection (1 paper, 2016). "Among the numerous qTUX-MS identified factors of interest, our study is the first to demonstrate the involvement of HMCES (or C3orf37) in viral infection." (PMID 27556644, 2016).
tumor (2 papers, 2020 to 2021). "We experimentally show that both HMCES disruption and A3A expression increase susceptibility of cancer cells to ionizing radiation (IR), oxidative stress, and ATR inhibition, strategies that are often applied in tumor therapies." (PMID 33788831, 2021).
cancer (1 paper, 2021). A tumor composed of atypical neoplastic, often pleomorphic cells that invade other tissues. "Together, our results identify additional druggable targets to be considered in A3A-expressing cancer cells and establish a central role for HMCES in preventing the toxicity of A3A expression." (PMID 33788831, 2021). "Together, these data further support a role for HMCES in tolerating endogenous A3A expression in cancer cells." (PMID 33788831, 2021). "Together, our data point to HMCES as an important dependency of cancer cells for survival and suggest that this can be exploited using combination therapies." (PMID 33788831, 2021). "Our results establish that HMCES is a key mediator of A3A toxicity in cancer cells." (PMID 33788831, 2021). "Further, this suggests that inhibiting HMCES would be selective for treating tumors undergoing certain types of DNA damage, such as APOBEC-mediated cytosine deamination, or in combination with specific therapeutic strategies, such as radiotherapy that is widely used in cancer treatment." (PMID 33788831, 2021). "In contrast, HMCES, UBA6, and ATXN7L3 appeared to have a more restricted pattern of sensitization to DNA damaging agents, indicating that they may represent better targets for selective killing of APOBEC-expressing cancer cells." (PMID 33788831, 2021).
HMCES also shares sentences with these, for which no sentence is quoted: Hepatic steatosis (2 papers); Obesity (2); Flavivirus Infections (1); liver fibrosis (1); metabolic disorders (1); metabolic dysfunction-associated steatohepatitis (1); steatosis (1).